CXCL10 (C-X-C motif chemokine ligand 10)
Diseases named in the same sentence as CXCL10 in open-access papers (continued):
Sharing a sentence is not in itself a finding about the gene and the disease.
infection (continued). "In this regard, it is interesting to note that both human and murine Nef-expressing astrocytes release CXCL10/IP-10, a chemokine shown to induce neuronal death, and that its neurotoxicity is more pronounced at 48 h than at 24 h after infection." (PMID 26066624, 2015). "Additional examination of tissue biopsies from patients with tissue infections depicted co-localization of extracellular histones and CXCL10, suggesting that the chemokine is released at the site of infection under disease conditions." (PMID 26646682, 2015). "Nod1 (C10) and its responsive genes Irf7 and Stat1 (C11) were elevated late during infection as well as interferon-induced genes Cxcl10, Ifit1-3, Iigp1 and Rsad2 (C7)." (PMID 26367386, 2015). "Within this group, IFNα, CCL4, CXCL1, and CXCL10 were upregulated following ArmΔGPC priming but prior to infection with Cl13, suggesting that these cytokines were upregulated not only upon Clone 13 infection but also by the priming agent." (PMID 25569216, 2015). "Though CXCL10 concentrations in plasma samples from patients suffering from mild infection were lower than in ICU patients, their levels were still significantly increased compared to those measured in samples from healthy donors." (PMID 26646682, 2015). "The results showed that PAMs infected with M. hyopneumoniae exhibited significantly increased expression of CCL4, CXCL2 and CXCL10 mRNA at 6 h post-infection, and decreased at a steady-state level, with maximal production at 6 h post-infection." (PMID 25098731, 2014). "Although we have previously reported that S. suis induces the production of CXCL10 from dendritic cells, gene upregulation in tracheal cells were only observed with swH1N1 infection in the present study." (PMID 24708855, 2014). "CXCR3 and its ligands (CXCL9, CXCL10, and CXCL11) are undoubtedly linked to the Th1 pattern and constitute an inflammatory pathway that coordinates the immune responses at sites of infection and inflammation." (PMID 24586509, 2014). "The chemokine CXCL10 is produced during infection and inflammation to activate the chemokine receptor CXCR3, an important regulator of lymphocyte trafficking and activation." (PMID 24890566, 2014). "In the liver, CXCL10 mRNA expression was increased at day 60 (2.1-fold) and at day 90 (2.2-fold), and was lower both at the early stage and the late stage of infection when compared to control mice." (PMID 24637903, 2014). "By contrast, significant, but modest, increases in mRNA production in response to infection were observed only for CXCL10 and CXCL11 in LASV-infected MP." (PMID 24421914, 2014). "Apical release of CXCL10 was enhanced in all treatment conditions with more pronounced levels detected in the combined MEM infection and IFN γ treatment." (PMID 25033426, 2014). "Further chemokine gene expression studies in brains of ECM-susceptible mice confirmed that CXCL10, CXCL9 and CCL5 and to lesser extent CCL2, CCL7, CCL3, CCL4 and CXCL2 are upregulated during infection with P. berghei ANKA." (PMID 24476686, 2014). "CXCR3-expressing CD8+ T cells, Th1 cells and NK cells that are recruited to the site of infection contribute to CXCL10 secretion by hepatocytes via the release of IFN-γ." (PMID 24646914, 2014). "Infection with MOPV induced the massive synthesis of CXCL10 and 11 mRNA in DC, whereas only modest levels of CXCL11 mRNA were detected in response to LASV stimulation." (PMID 24421914, 2014). "Monitoring of 15 cytokines showed that those, which are known to be increased early in HIV-1/SIVmac pathogenic infections, such as IL-15, IFN-α, MCP-1 and CXCL10/IP-10, were significantly increased in AGMs as well." (PMID 24991927, 2014). "In those studies, blockade of CXCL10 decreased myeloid cell recruitment to the site of infection, decreased bacterial clearance and increased mortality." (PMID 24890566, 2014).
infection (continued). "CXCL10−/− mice or mice receiving anti-CXCL10 neutralizing antibodies over the course of P. berghei-ANKA infection were found to have reduced cerebral intravascular inflammation and were protected against fatality." (PMID 24476686, 2014). "Well differentiated HBE cells demonstrated significant synergistic induction of CXCL10 mRNA following infection with the MEM influenza virus and treatment with IFN γ." (PMID 25033426, 2014). "These gene lists also featured a number of inflammatory cytokines and chemokines involved in chemotaxis of myeloid and lymphoid cell types to the sites of infection (Ccl4, Ccl5, Ccl7, Ccl12, Cxcl9, Cxcl10)." (PMID 23853600, 2013). "Consistent with the function of C16 inhibiting the innate immune response to DNA, this effect was significant in the first 2 d post infection (p.i.)at 24 and 48 h p.i. for Cxcl10, and at 24 h p.i. for Il-6." (PMID 24098118, 2013). "Cytokines and chemokines such as CCL2 (MCP-1), CCL3 (MIP1α), CCL5 (RANTES), and CXCL10 (IP10) are responsible for activating leukocytes and attracting them to the lung compartment to clear infection." (PMID 23441208, 2013). "The in vitro observations indicate positive feed-backs between IFN-γ and CXCL10 production for better control of the infection." (PMID 23801993, 2013). "Induction of IFN-λ1, and ISGs CCL-5 and CXCL-10 was significantly higher in COPD pBECs after infection compared to that in healthy pBECs." (PMID 23384071, 2013). "Levels of CXCL10 mRNA induced by Benin 97/1 infection in vitro were lower than for OURT88/3, contrasting with the data from in vivo infections described here." (PMID 24083897, 2013). "The chemokines CCL2, CCL5, CXCL1 as well as CXCL10 are all important for recruiting immune cells to the site of infection, and by inhibiting their biological activity, P. gingivalis is able to modulate and diminish the level of infiltrating immune cells." (PMID 23841502, 2013). "We used ATV adjunctively with ARM treatment of established infections and iteratively repurposed a drug selected for its ability to modulate CXCL10 and inflammatory responses in murine ECM." (PMID 23630573, 2013). "The control group showed significant increase in CXCL10 on day 11, as previously reported, compared to day 5 post-infection, p<0.001." (PMID 23630573, 2013). "In this pig low levels of CXCL10 were detected in the sample pre-infection increasing in amount dramatically by 5 dpi." (PMID 24083897, 2013). "Accordingly, mice were orally inoculated with cysts, and relative levels of CXCR3, CXCL9 and CXCL10 mRNA expression were measured over the course of acute infection." (PMID 24130498, 2013). "CBMC production of CCL4 and CXCL10 was near maximum at 12 hours and was still detected at 48 hours post-infection." (PMID 22479521, 2012). "Examining chemokine expression, we found that the protein and mRNA levels of CXCL10 were significantly elevated in the serum and liver of infected mice at days 0.6 and 1 after infection." (PMID 23050007, 2012). "Our data showed a two- to three-fold increased induction of CXCL10 in response to HSV-1-infection when macrophages were subjected to IFI16 knock-down." (PMID 23062757, 2012). "NY/238 infection markedly stimulated CXCL10 mRNA, NY/238 virus also triggered an early increase in the expression of RIG-I and IFNA1 genes and increased mRNA levels of antiviral gene ISG56 and CCL chemokine CCL5." (PMID 22396727, 2012). "As production of interferon gamma by these cells is contested, it is possible that the generation of CXCL10 is either a direct effect of NiV proteins or is induced via NiV-activation of interferon beta, following infection." (PMID 22393386, 2012). "Cxcl10, which was assayed only after 6 h, was downregulated in expression by infection (P < 0.05 for both Y. pestis strains) but showed greater downregulation when YopM was present (P < 0.05)." (PMID 23248776, 2012).
infection (continued). "In lung and spleen the level of CXCL10 initially increased, but decreased on the last day that preceded lethal outcome of the infection." (PMID 22393386, 2012). "Dengue virus alone did induce consistent upregulation of CXCL10 in KU812 cells, but this level was still greater than 20,000-fold less than the over one million-fold increase in CXCL10 mRNA after infection with dengue virus in the presence of antibody." (PMID 22479521, 2012). "CXCL10 expression was mute in cases of NC8 infection compared with NC2 and NC11 throughout the study period (P < 0.0001)." (PMID 22672588, 2012). "CXCL10 competes with dengue virus for binding to cell surface heparan sulfate, thereby reducing viral uptake and infection of cells." (PMID 22574162, 2012). "Our results demonstrate that NiV-infection induces rapidly production of CXCL10 in primary endothelial cells." (PMID 22393386, 2012). "The depletion of CXCL10 by anti- CXCL10 mAbs for the duration of 4 weeks following infection (5 weeks following vaccination) abrogated the protective immunity induced by vaccination with SLA-CpG-DCs." (PMID 23144947, 2012). "The baseline expression of CXCL10 was observed in all organs and increased during the course of infection, particularly in brain and kidney." (PMID 22393386, 2012). "This suggests an elevated systemic expression of Foxp3 mRNA and protein in CXCL-10-/- than in WT mice during the infection." (PMID 21439091, 2011). "CXCL9 and CXCL10 levels in vaginal washes were significantly different after infection with our different strains." (PMID 21283640, 2011). "Only CXCL10 expression was significantly attenuated in TLR4 mutant mice at day 3 post-infection, whereas the majority of mediators, including CCL2, CXCL1, and IL-1β were similar between TLR4 mutant and WT mice across all time points examined." (PMID 21496301, 2011). "Foxp3 mRNA and protein in brain and PBMC's of CXCL-10-/- mice was significantly up-regulated (p < 0.05) by day 4 post-infection (p.i) compared with WT." (PMID 21439091, 2011). "Disease associated with highly pathogenic influenza viruses and the clinical manifestations that ensue in humans can be mediated by the proinflammatory response (e.g., TNF-α, IL-6, CCL2, CCL3, and CXCL10) initiated by the host in response to infection." (PMID 21829352, 2011). "Normalizing the mRNA fold change to a constant amount of MNV RNA established that in all cases examined (CXCL10, ISG54 and IFN-Beta) the M1 infection causes a much more rapid induction of the innate immune response." (PMID 22174679, 2011). "In all mice, P. berghei infection induced significant amount of Foxp3 mRNA expression in brain and PBMCs in CXCL-10-/- at day 4 post-infection when compared with WT." (PMID 21439091, 2011). "Induction of IL-2 in peripheral blood started early at day 2 and was significantly elevated (p < 0.05) at day 4 post-infection compared with uninfected controls in CXCL-10-/- mice." (PMID 21439091, 2011). "Infection of glial cells leads to up-regulation of CXCL10, IL-1β and IDO, and together with expression of MMP by infected astrocytes result in loss of tight junction and increased BBB permeability." (PMID 21994755, 2011). "Protein levels in the CSF showed a significant increase in CXCL10 expression when comparing ID vs. IS at 72 h after infection." (PMID 21412436, 2011). "In the CSF of infected animals, CXCL10 was upregulated on the protein level by dex at 72 h after infection." (PMID 21412436, 2011). "Western Blots analysis of Foxp3 protein expression indicated that Foxp3 proteins (48 kD) in infected CXCL-10-/- peaked at day 4 at higher level than in uninfected controls at day 2 and 8 post-infection." (PMID 21439091, 2011). "It was observed that there is a significant induction of IL-2 in CXCL-10-/- than in WT, at day 2 (~40%,) and 4 (~80%, p < 0.05) post-infection." (PMID 21439091, 2011).
infection (continued). "Brain and PBMC Foxp3 expression induced by P. berghei were significantly up-regulated in CXCL-10-/- mice at Day 4 post-infection compared with WT." (PMID 21439091, 2011). "Analysis of C. rodentium-infection in Cxcl10 knockout mice revealed that bacterial clearance was impaired in C. rodentium-infected Cxcl10 knockout mice." (PMID 20532209, 2010). "In X4LAI.04 infected tissues treated with flagellin, there was a significant increase in the levels of CCL3, CCL4, and CXCL10 (by 130%, 60%, and 30%, respectively; p<0.047, n = 6) already on day 3 post-infection." (PMID 20862220, 2010). "In summary, up-regulation of mRNA for TNF-α, CCL-5/RANTES, and CXCL-10/IP-10 was found to be more prominent during the early phase of infection with H5N1/2004 and H9N2/1997 viruses than those induced by H1N1/2002 virus." (PMID 21108843, 2010). "IL-6 and CXCL-10/IP-10 were induced in H9N2/1997 infections; but at relatively lower fold-changes than those of H5N1 throughout the time course examined." (PMID 21108843, 2010). "Neutralization or genetic silencing of CXCL10 following infection with HSV, JHMV, and WNV dramatically reduces T cell trafficking into the CNS, thus preventing efficient viral control and often resulting in poor resolution." (PMID 20686655, 2010). "At 6 hours post-H5N1/2004 infection, there were marked increase in the expression of CXCL-10/IP-10 and CCL-5/RANTES (60-120 folds); while there were only relatively minor increase in IL-6 and IL-8 expression (2-10 folds)." (PMID 21108843, 2010). "More recently, increase CXCL10 and IL-10 expression were observed upon infection of human monocytes with L. braziliensis." (PMID 20559550, 2010). "Virally, stimulatedpDC produces chemokines, such as CCL3 (MIP-1a), CCL4 (MIP-1b), CCL5 (RANTES),CXCL8 (IL-8), and CXCL10 (IP-10) which stimulate Th1, and NK cells homing tosite of infection through IP-10 and CCL4, respectively." (PMID 19190769, 2008). "Some genes related to the inflammatory response, such as Cxcl10, Clu and antigen presentation, such as B2m, Fcer1g showed over-expression only at 72 and 96 hr post infection." (PMID 18558011, 2008). "CXCL10 is captured by cell surface heparan sulfate proteoglycans from the fluid phase and forms a concentration gradient around the site of infection." (PMID 23675028, 2007). "In particular CXCL10 (IFNγ-inducible protein of 10 kDa, IP-10) is generated at high levels very early after infection." (PMID 23675028, 2007). "Among chemokines, CXCL10 stands out of the mass, because of its massive and unique expression very early after infection of mice with LCMV." (PMID 23675028, 2007). "CXCL10 plays a key role in orchestrating the cellular trafficking towards the site of infection and subsequently imprints a pattern for the detrimental autoaggressive immune response against the islet of Langerhans." (PMID 23675028, 2007). "CXCL10 has an essential function in recruiting immune cells to areas of infection or inflammation." (PMID 41463372, 2025). "The evasion of fungal immune control mechanisms with down-regulated Th1 (IFN-γ, TNF-α, and IL-2) and Th17 T cell cytokines (IL-17A) and CXCR3+ T cell chemoattractant chemokine (CXCL10) responses, allows more vigorous replication of Cryptococcus and overwhelming infection." (PMID 39928682, 2025). "Moreover, only S- and S/N-immunized animals had reduced levels of CCL2, CCL3, CCL4 and CXCL10 chemokines after the infection compared to the PBS group." (PMID 41306976, 2025). "In summary, CXCL10 serves as a significant chemokine that plays a crucial role in mediating immune responses and inflammation, as well as in attracting immune cells to areas impacted by infection or inflammation." (PMID 41463372, 2025). "However, all chemokines, except CXCL10, and receptors were significantly upregulated in all infection groups at 14 dpi." (PMID 40459260, 2025).
infection (continued). "Increased chemotactic signals, such as Cxcl9 and Cxcl10, at the base of the muscularis might be responsible for the accumulation of short-lived effector cells observed in the few days after infection." (PMID 39843748, 2025). "Notably, among all cytokines and chemokines analyzed, CXCL10 was the only one displaying significantly increased serum levels in acutely infected mice (2 dpi) prior to returning to undetectable levels upon infection resolution (12 dpi)." (PMID 40920821, 2025). "The three most upregulated chemokines during infection were Ccl5, Cxcl9, and Cxcl10." (PMID 40635167, 2025). "CXCL10 secretion at 24 h after infection with 1 × 104 and 1 × 105C." (PMID 40181464, 2025). "However, only a few inflammatory mediators remained elevated at 28 days post-infection in the hippocampus in the B.1.351 model (IL-6) and in the CSF in the AAV model at 7 weeks post-infection (CXCL10, CCL11)." (PMID 39861887, 2025). "During infection, inflammatory cytokines such as IL-6, IL-8, and CXCL-10 are often elevated." (PMID 40002820, 2025). "Four major features characterized these cells: 1) a dominant CD163-expressing population that emerges during acute infection before dissipating, 2) a major source of CXCL10 expression, 3) a high enrichment in viral RNA, and 4) the induction of robust antiviral responses." (PMID 40920821, 2025). "Other types of infection or inflammation could potentially lead to an elevated nasal CXCL10 concentration, such as infection with other microbes or allergic inflammation." (PMID 40543450, 2025). "Interestingly, here we find CXCL10 among the top down-regulated genes at the first hour of infection, suggesting the silencing of immune cell recruitment during early response, and the expression stays similarly suppressed throughout the time-course." (PMID 39863683, 2025). "Accordingly, expression of Cxcl9, Cxcl10, and Cxcl16 was increased earlier, at 14 days after infection in lungs of C57BL/6 compared with C3HeB/FeJ mice, with expression most pronounced in macrophages, conventional dendritic cells (cDCs), and, in the case of Cxcl10, neutrophils." (PMID 40986319, 2025). "Additionally, elevated levels of CXCL10 have been detected in human samples from infections with various viruses, including ZIKV, DENV, MV, HIV-1, and several respiratory viruses." (PMID 39861921, 2025). "Notably, macrophages have been shown to recruit Vγ9Vδ2 T cells to the site of infection through CXCL10 and CXCR3 receptor-ligand interactions." (PMID 41055972, 2025). "CXCL10 levels were significantly reduced in Berb-treated group compared to the infection group." (PMID 39640591, 2024). "Induced by interferon-γ, CXCL10 plays an important role in both innate and adaptive antiviral immune responses by inducing chemotaxis of NK cells, macrophages, dendritic cells, and T lymphocytes to sites of infection and polarizing Th1 cells." (PMID 38756971, 2024). "Having seen that the addition of chemokines over 3 days during the peak of T cell recruitment altered the response to RSV infection and protection against secondary re-infection, we explored if a single dose of CCL5 or CXCL10 on day 7 after infection would be sufficient to enhance TRM recruitment." (PMID 39749186, 2024). "Expression of luciferase, as well as endogenous IFIT-2 and CXCL-10 was significantly reduced following ruxolitinib treatment of Gag-LUC-infected cells indicating that infection with this Gag-LUC fusion virus induces type I IFN production, to induce endogenous ISG and IFN reporter expression." (PMID 38778414, 2024). "In addition, several members of the chemokine family of GPCRs have been observed to be upregulated in Calu-3 cells upon infection, including, among others, CXCL10, CXCL11 and CCL2." (PMID 38786015, 2024). "The secretion of chemokine IP10 (also known as CXCL10) has been shown to trigger the activation and recruitment of monocytes, NK cells, and T cells to sites of tissue damage associated with infection." (PMID 39290698, 2024).